BLK (BLK proto-oncogene, Src family tyrosine kinase)
Description:
Non-receptor tyrosine kinase involved in B-lymphocyte development, differentiation and signaling (By similarity). B-cell receptor (BCR) signaling requires a tight regulation of several protein tyrosine kinases and phosphatases, and associated coreceptors (By similarity). Binding of antigen to the B-cell antigen receptor (BCR) triggers signaling that ultimately leads to B-cell activation (By similarity). Signaling through BLK plays an important role in transmitting signals through surface immunoglobulins and supports the pro-B to pre-B transition, as well as the signaling for growth arrest and apoptosis downstream of B-cell receptor (By similarity). Specifically binds and phosphorylates CD79A at 'Tyr-188'and 'Tyr-199', as well as CD79B at 'Tyr-196' and 'Tyr-207' (By similarity). Also phosphorylates the immunoglobulin G receptors FCGR2A, FCGR2B and FCGR2C. With FYN and LYN, plays an essential role in pre-B-cell receptor (pre-BCR)-mediated NF-kappa-B activation (By similarity). Also contributes to BTK activation by indirectly stimulating BTK intramolecular autophosphorylation (By similarity). In pancreatic islets, acts as a modulator of beta-cells function through the up-regulation of PDX1 and NKX6-1 and consequent stimulation of insulin secretion in response to glucose. Phosphorylates CGAS, promoting retention of CGAS in the cytosol.
Synonyms: MGC10442; MODY11
Tractability: Small molecule: an approved drug acts on it; a high-quality ligand is known; it belongs to a druggable protein family. Antibody: UniProt places it where antibodies can reach, with medium confidence; its Gene Ontology location is reachable by antibodies, with medium confidence. PROTAC: it is named in the literature on targeted protein degradation; UniProt records ubiquitination sites on it; ubiquitination databases record sites on it; its protein half-life has been measured; a small molecule that binds it is known.
Target class: Kinase; TK protein kinase group; Enzyme; Protein Kinase; Tyrosine protein kinase Src family
Chemical probes: DGY-06-116 (high quality)
Gene: Protein-coding gene on chromosome 8 (11,486,894 to 11,564,599, forward strand). Ensembl gene ENSG00000136573.
Subcellular location: Cell membrane
Subcellular location (Human Protein Atlas): Nucleoplasm
Pathways (Reactome):
Gene expression (Transcription): RUNX1 regulates transcription of genes involved in BCR signaling
Immune System: Antigen activates B Cell Receptor (BCR) leading to generation of second messengers
Gene Ontology:
Molecular function: non-membrane spanning protein tyrosine kinase activity; protein binding; protein tyrosine kinase activity; signaling receptor binding; ATP binding; protein kinase activity
Biological process: B cell receptor signaling pathway; peptidyl-tyrosine phosphorylation; positive regulation of insulin secretion; cell differentiation; cell surface receptor protein tyrosine kinase signaling pathway; intracellular signal transduction; immune response-activating cell surface receptor signaling pathway
Cellular component: cytosol; plasma membrane
Genetic constraint (gnomAD): Loss-of-function variants: 63 observed, 59.98 expected, observed/expected ratio (o/e) 1.05, 90% interval 0.86 to 1.29. The synonymous counts are far from expectation, so gnomAD's model fits this gene poorly and the ratio says little. Missense variants: 825 observed, 647.06 expected, observed/expected ratio (o/e) 1.27, 90% interval 1.2 to 1.35. Synonymous variants: 343 observed, 272.3 expected, observed/expected ratio (o/e) 1.26, 90% interval 1.15 to 1.38.
Gene-disease validity (ClinGen):
ClinGen rates the evidence that BLK causes each of these diseases.
monogenic diabetes (autosomal dominant): Refuted. Diabetes mellitus that is caused by mutations in a single gene.
Homologues: Orthologues: chimpanzee BLK (99% identical), macaque BLK (97% identical), dog BLK (88% identical), pig BLK (87% identical), rat Blk (87% identical), mouse Blk (86% identical), guinea pig BLK (86% identical), rabbit BLK (86% identical), tropical clawed frog lck (64% identical), zebrafish lck (60% identical). Paralogues in human: HCK (62% identical), LCK (61% identical), LYN (60% identical), FYN (57% identical), SRC (55% identical), YES1 (55% identical), FGR (54% identical), FRK (45% identical), ABL2 (41% identical), ABL1 (40% identical), SRMS (39% identical), TEC (37% identical), and 20 more.
Diseases named in the same sentence as BLK in open-access papers:
BLK is named in the same sentence as 85 diseases in open-access papers, as found by Europe PMC text mining. Sharing a sentence is not in itself a finding about the gene and the disease. The quoted sentences say what the papers report.
MODY (23 papers, 2012 to 2025). "The BLK gene has been associated with Maturity Onset Diabetes of the Young (MODY), a condition characterised by early-onset hyperglycaemia." (PMID 40682692, 2025). "Lastly, BLK is linked to MODY in individuals with higher BMI, which is in consistent with the phenotype of our patient with a history of strong autosomal-dominant inheritance." (PMID 39504571, 2025). "To date, 17 pathogenic variants in BLK have been reported; however, the role of this gene as a definitive cause of MODY remains to be fully clarified." (PMID 41153735, 2025). "Based on all the previous information, MODY was suspected, and genetic testing was done, which showed rare variants in the BLK and ABCC8 genes and suggested a co-occurrence of MODY11 and MODY12." (PMID 39391454, 2024). "Not all carriers of BLK pathogenic variants exhibit diabetes, and thus BLK-MODY has incomplete penetrance." (PMID 36361703, 2022). "Moreover, the consistent presence of the BLK gene variant in limited cases of co-inheritance raises questions about its causative role in MODY, suggesting a need for further investigation into its clinical significance." (PMID 39391454, 2024). "The only BLK coding variant (p.A71T) reported to cause MODY was later found to be very common in normoglycemic individuals, showing that the variant is too common to cause MODY, raising doubt over the aetiological role of BLK." (PMID 36361703, 2022). "Notably, the associations between BLK mutations and MODY penetrance has been indecisive." (PMID 36613572, 2022). "We recently demonstrated that variants in BLK, KLF11, and PAX4 reported to cause MODY are common in the population, have limited co-segregation, and lack enrichment in MODY cases compared to controls." (PMID 40779032, 2025). "Of the 89 eDia3 patients, 10 (11.2%) carried likely pathogenic variants in genes (KLF11, GCK, ABCC8, PAX4, BLK and HNF1A) of MODY." (PMID 35921062, 2022). "In summary, we identified variants in BLK, CEL, KLF11, PDX1, and PAX4 that may contribute to various forms of diabetes, including rare MODY subtypes." (PMID 41153735, 2025). "Own4 reported 16 genes associated with MODY, including BLK, PAX4, and KLF11, but their genetic evidence was not well documented." (PMID 38095268, 2024). "Unlike other subtypes of MODY, BLK–MODY is not highly penetrant; instead, it is described as having incomplete penetrance, meaning that several BLK mutations do not directly or necessarily cause diabetes (although they are still pathogenic)." (PMID 36573710, 2022). "Given the lack of evidence for coding variants in BLK as a cause of MODY, it is unlikely that noncoding variants would be pathogenic." (PMID 36361703, 2022). "Interestingly, in this study population, utilizing the NGS we have identified MODY variants in NEUROD1, PDX1 and BLK genes in comparison to the more commonly reported HNF4A, GCK and HNF1A gene variants." (PMID 28095440, 2017). "Laver et al5 also demonstrated by variant— and gene‐level genetic evidence that BLK, KLF11, or PAX4 was not a cause of MODY, and they proposed that these three genes should be removed from MODY diagnostic genetic testing." (PMID 38095268, 2024). "We did not include BLK, KLF11 and PAX4 in our gene panel due to lack of strong genetic evidence supporting the gene-disease association for MODY." (PMID 34789499, 2022). "To date, 14 disease genes for MODY are identified; most of them are transcription factors MODY1 (HNF4A), MODY3 (HNF1A), MODY4 (PDX1), MODY5 (HNF1B), MODY6 (NEUROD1/BETA2), MODY7 (KLF11), MODY8 (CEL), MODY9 (PAX4), MODY11 (BLK), and MODY14 (APPL1)." (PMID 31145732, 2019).
MODY (continued). "However, some authors have argued that there is insufficient evidence to support a causal role for BLK, KLF11, or PAX4 variants in MODY pathogenesis, and these genes should not be routinely included in diagnostic testing." (PMID 41153735, 2025).
autoimmune disease (18 papers, 2011 to 2025). A disorder resulting from loss of function or tissue destruction of an organ or multiple organs, arising from humoral or cellular immune responses of the individual to their own tissue constituents. "One locus, rs2618471 (near BLK), had many autoimmune disease pleiotropic associations, including SjD, systemic sclerosis, systemic lupus erythematosus, and rheumatoid arthritis." (PMID 40166553, 2025). "This is likely to reflect a common mechanism for BLK-mediated genetic risk in autoimmune diseases associated with BLK." (PMID 34199962, 2021). "SNP rs2254546 is located between FAM167A and BLK gene loci, a region known to have genetic associations with autoimmune diseases like systemic lupus erythematosus, rheumatoid arthritis, and systemic sclerosis." (PMID 32678208, 2020). "Small sample size and the low statistical power of previous studies contributed to our interest in conducting a comprehensive and precise analysis of the association between BLK polymorphisms and autoimmune diseases." (PMID 28885337, 2017). "We also conducted subgroup analyses to further explore the potential effects of the patients’ ethnicities, the source of the controls, and the types of illness with the association of BLK polymorphisms and autoimmune diseases." (PMID 28885337, 2017). "Meta-analysis for the association between BLK (rs13277113, rs2736340, rs4840568) polymorphism and autoimmune diseases by types of diseases." (PMID 28885337, 2017). "This meta-analysis indicated that the BLK (rs13277113, rs2736340, rs4840568) polymorphisms were associated with an increased risk of autoimmune diseases." (PMID 28885337, 2017). "The findings from this meta-analysis, based on 68,874 cases and 90,684 controls of autoimmune diseases patients, found that the BLK polymorphisms rs13277113, rs2736340, and rs4840568 are significantly associated with susceptibility to autoimmune disease." (PMID 28885337, 2017). "In their study, they conducted a meta-analysis focusing on 21 studies and concluded that the BLK rs2736340 polymorphism is associated with several autoimmune diseases." (PMID 28885337, 2017). "The results revealed that BLK polymorphisms were closely associated with the risk of autoimmune diseases in all ethnicities; however, the correlation was stronger in Asian group than in other racial groups." (PMID 28885337, 2017). "Even so, the results indicated that the A allele of BLK rs13277113 and rs4840568 and the T allele of BLK rs2736340 were a risk factor for autoimmune diseases." (PMID 28885337, 2017). "The fact that BLK risk alleles are shared by multiple autoimmune diseases suggests that the risk alleles promote disease through a common underlying mechanism." (PMID 24637841, 2014). "Genome-wide association studies have found that multiple single nucleotide polymorphisms (SNPs) in the BLK locus are associated with autoimmune disorders in several populations, including systemic lupus erythematosus, rheumatoid arthritis, systemic sclerosis, and so forth." (PMID 37871014, 2023). "It is largely unknown how SNP risk alleles of BLK or its aberrant expression eventually causes autoimmune diseases." (PMID 37871014, 2023). "Furthermore, on the basis of the pathogenicity of BLK polymorphisms, our research provides a meaningful therapeutic strategy for autoimmune diseases." (PMID 28885337, 2017). "This meta-analysis shows that the BLK (rs13277113, rs2736340, rs4840568) polymorphisms may be a risk factor for developing autoimmune diseases, especially for Asian populations and SLE." (PMID 28885337, 2017). "Primary SS is an autoimmune disease with a genetic basis in which at least 40 gene risk factors may be involved, including BLK, IRF5, STAT4, and the HLA locus." (PMID 26379672, 2015).
autoimmune disease (continued). "Given the well-documented role of B cells in autoimmune disease development and pathogenesis, these data suggest that BLK risk alleles promote development of SLE by altering BCR signaling responses and, by extension, B cell development, function, and tolerance." (PMID 24637841, 2014). "BANK1 and BLK have been associated to human autoimmune diseases." (PMID 23555801, 2013). "Together, our results outline a new signaling pathway in B-lymphocytes including the autoimmunity associated genes BANK1, PLCg2 and BLK and they fill a gap in our understanding of the mechanistic relation between associated alleles in human autoimmune diseases and B-cell physiology in particular." (PMID 23555801, 2013). "On the other hand, the interaction between BLK with other genes and environmental conditions may be important in the susceptibility of KD and other autoimmune disorders." (PMID 24023612, 2013). "This suggests a trend indicating that the relationship between BLK and more autoimmune diseases requires further study in the future." (PMID 38997544, 2024). "Accordingly, we conclude that SNPs in the BLK locus increase risk to SLE, and to other autoimmune diseases, through the dysregulation of a proinflammatory cytokine network." (PMID 24637841, 2014). "Accumulating evidence has shown that BLK is strongly involved in the development of a wide variety of autoimmune diseases." (PMID 24632671, 2014). "The region contains at least 50 genes, among which the BLK - B lymphocyte kinase - gene that has been associated with systemic lupus erythematosus (SLE), rheumatoid arthritis (RA) and other autoimmune diseases." (PMID 23730202, 2012). "In addition, according to a genome-wide association study, autoimmune disease (e.g., SLE and rheumatoid arthritis) and MCLS share common candidate genes (e.g., BLK and CD40)." (PMID 38125818, 2023). "In addition, we also included 33 studies of BLK rs13277113 and 6 studies of BLK rs4840568 to systematically explore the relationship between BLK and autoimmune diseases." (PMID 28885337, 2017). "Our research found that BLK can act as an influencing factor on autoimmune diseases." (PMID 28885337, 2017). "Thus, BLK has been deemed a meaningful candidate gene for autoimmune diseases." (PMID 28885337, 2017). "However, none of the family members carrying BLK mutations reported a history of autoimmune disorders." (PMID 24023612, 2013). "Four genes (BLK, HSPA1A, IL12A, NEU1) have been targeted for drug development in autoimmune diseases and other conditions." (PMID 38997544, 2024). "B-cell lymphocyte kinase (BLK) is an inhibitor of B cells that has an important influence on several autoimmune diseases, but there is a lack of comprehensive analysis of its association with autoimmune diseases." (PMID 28885337, 2017). "According to that study, BLK rs2736340 was identified as one of the risk genes for adult and juvenile dermatomyositis in Europeans after screening of 141 non-MHC SNPs that had previously been associated with autoimmune diseases." (PMID 24632671, 2014).
systemic lupus erythematosus (18 papers, 2012 to 2025). An autoimmune multi-organ disease typically associated with vasculopathy and autoantibody production. "Two lupus-associated BLK promoter variants, namely, rs922483 and rs1382568, control BLK expression in cell type- and developmental-stage-specific manner adding even more complexity." (PMID 39624492, 2024). "The BLK locus is associated with various immune diseases, including rheumatoid arthritis, systemic lupus erythematosus, systemic sclerosis, and KD." (PMID 34830213, 2021). "Risk alleles of the BLK gene associated with systemic lupus erythematosus (SLE) and KD are linked to reduced expression of BLK." (PMID 34830213, 2021). "We next tested the effect of the BLK variants on lupus development in vivo using CRISPR/Cas9-generated mice bearing the orthologue of human BLKR131W, BlkR125W." (PMID 31101814, 2019). "In this study we validate the novel PCA methodology to identify inversion status in our large Caucasian cohort and evaluate this potential confounding factor in regard to the known BLK association with lupus." (PMID 25545785, 2014). "In a recent lupus functional study of BLK the risk allele (T) at rs922483 was shown to reduce proximal BLK promoter activity and modulated alternative promoter usage." (PMID 25545785, 2014). "BLK, which encodes B lymphoid kinase, was recently identified in genome wide association studies as a susceptibility gene for systemic lupus erythematosus (SLE), and risk alleles mapping to the BLK locus result in reduced gene expression." (PMID 24637841, 2014). "Although systemic lupus erythematosus causal variants at the FAM167A-BLK locus are thought to reside in the BLK promoter region, our results reveal that genetic variants at distal regulatory elements modulate promoter activity, changing BLK and FAM167A gene expression and disease risk." (PMID 36160011, 2022). "Moreover, the presence of additional lupus-predisposing gene variants in SLE patients may enhance the BLK defects." (PMID 31101814, 2019). "Furthermore, the co-segregation of variants in BANK1 and BLK in two families suggests that sporadic lupus may occur upon inheritance or de novo occurrence of two or more rare variants with strong effects that act together to cause disease." (PMID 31101814, 2019). "BLK is a member of the SRC family of kinases specifically expressed in the B-cell lineage, and its gene has been linked to systemic lupus erythematosus susceptibility." (PMID 36821545, 2023). "An example of heterogeneity is the relationship between genetic variants from the BLK and TNFSF4 genes in systemic lupus erythematosus." (PMID 33901204, 2021). "We demonstrate the functional consequences of rare and low frequency missense variants in the interacting proteins BLK and BANK1, which are present alone, or in combination, in a substantial proportion of lupus patients." (PMID 31101814, 2019). "In summary, our results add another dimension to the complexity of regulation of BLK in lupus and demand further studies to fully elucidate the interaction of inversion status and candidate functional variants." (PMID 25545785, 2014). "Therefore, both of these risk conditions i.e., non-inverted status (that we found to be more common in lupus cases) and risk allele-T synergistically tend to decrease expression of BLK in lupus patients." (PMID 25545785, 2014). "These 31 loops involved 22 lupus haplotypes, with ETV3-FCRL5, BLK, and IRF8 haplotypes containing more than one significantly differential loop." (PMID 40437445, 2025). "BANK1 and BLK belong to the pleiotropic autoimmune genes; recently, epistasis between BANK1 and BLK was detected in systemic lupus erythematosus." (PMID 23646104, 2013).